CD24 (CD24 molecule)
Diseases named in the same sentence as CD24 in open-access papers (continued):
Sharing a sentence is not in itself a finding about the gene and the disease.
cancer (continued). "Genotyping for CD24 copy number variation could provide a simple selection or stratification factor to identify populations of interest for cancer risk and treatment subtype, and its exploration as a predictive biomarker is warranted." (PMID 31244889, 2019). "In addition to the immunological functions, recent studies have implicated CD24 function in tumorigenesis and progression of multiple cancer types, including carcinomas in lung, prostate, ovarian, breast, and brain." (PMID 31244889, 2019). "CD44H, CD44v6 and CCR6 molecules may play a role in attachment of TMVs to cancer cells, while HER-2 associated with CD24 may be involved in promoting growth of cancer cells." (PMID 30925930, 2019). "It is certainly convinced that the oncogenic features associated with CD24 amplification cancers could influence response to BRCA treatment strategies." (PMID 31244889, 2019). "CD24 is a major player in many signal pathways, and is associated with inflamation and cancer." (PMID 29390019, 2018). "We also investigated whether autophagic and PPARγ-mediated pathways could modify a phenotype aspect linked to cancer stem cells (CSCs) population, measured by CD24/CD44 differential expression." (PMID 28932171, 2017). "Hence, in CD24-positive cancer cells, EGFR keeps its association with lipid rafts on the membrane that is necessary for its signaling transduction and reducing its internalization and degradation." (PMID 26830684, 2016). "CD44H, CD44v6 and CCR6 molecules may play a role in attachment of TMV to cancer cells, while HER-2 associated with CD24 be involved in promoting cancer cells growth." (PMID 26626416, 2015). "Although the mechanism of cancer progression caused by expressional alterations remains unknown, CD24 overexpression may be considered as a marker of GC that indicates invasiveness." (PMID 25503963, 2014). "Additionally, high CD24 expression may be linked to the formation of cancer stem cells, which are more resistant to treatment, making cancer more challenging to cure." (PMID 38273373, 2024). "Fluorescence-activated cell sorting (FACS) using CD44 and CD24 as markers revealed that HMLE-EMT cultures likewise contained a distinct subpopulation of cells carrying the CD44+CD24low/− antigenic phenotype associated with so-called mesenchymal cancer stem cells (CSC)." (PMID 36551699, 2022). "Therefore in models in which CD4 T cells promote cancer development, one may expect a different consequence of targeted mutation of the Cd24 gene." (PMID 29423273, 2018). "Therefore, CD24 may present a promising target to inhibit the unwanted development of myofibroblasts or even myofibroblast cell-like carcinoma-associated fibroblasts from hBMSCs." (PMID 26788063, 2016). "Given that the escape of cancer cells from immune surveillance is required for metastasis, it is possible that CD24 promotes metastasis through immune escape and this may explain the association of high CD24 expression with shorter DMFS in TNBC subtype." (PMID 26444008, 2015). "Additionally, we have presented some evidence that the analysis of isolated CD44 and CD24 immunoexpression or the CD44/CD24 immunophenotypes could give a prognostic informations associated to clinicopathologic features Salivary Gland Malignant Neoplasms." (PMID 23419168, 2013). "Studies have demonstrated that the overexpression of CD24 in cancer cell lines enhances cell proliferation and adhesion through integrin activation." (PMID 41585138, 2026). "CD24 expression is upregulated in many cancers, and research suggests that CD24 functions as an oncogene, promoting cell growth, migration, and invasion." (PMID 41585138, 2026). "Functionally, ATN significantly inhibited proliferation, induced apoptosis, and suppressed tumorsphere formation and CD44+/CD24- cancer stem cell (CSC) population in CRPC cells." (PMID 42158813, 2026).
cancer (continued). "CD24 was considered as a possible specific progenitor marker due to its expression by human intestinal epithelial stem cells as well as by a number of cancer stem cells." (PMID 40299654, 2025). "CD24 can activate the proliferation of cancer cells through the CD24-dependent MAPK pathway, in which extracellular regulatory protein kinase (ERK) and p38 mitogen-activated protein kinase (p38 MAPK) are key factors." (PMID 40486886, 2025). "By engaging Siglec-10, CD24 acts as a “don’t eat me” signal, preventing macrophage-mediated phagocytosis of cancer cells." (PMID 41551164, 2025). "Below, we will further explore the current preclinical evidence of CD24 in promoting cancer drug resistance and progression." (PMID 40486886, 2025). "PPAB001 disrupts the interaction between CD47 and its receptor SIRPα, as well as between CD24 and Siglec-10, thereby promoting the phagocytic activity of macrophages against cancer cells." (PMID 40330466, 2025). "When targeting CD24 for cancer treatment, we can not only directly block CD24 but also target its ligand siglec-10, as well as enhance the functions of immune cells for treatment, or even combine these approaches." (PMID 40486886, 2025). "Beyond its established roles in immune modulation, CD24 exhibits multifaceted functions relevant to cancer biology." (PMID 40777020, 2025). "CD24 can also rely on altering the activity of external immune cells to regulate the progression of cancer." (PMID 40486886, 2025). "The emergence of radiochemotherapy resistance during cancer treatment has also been found to be closely related to CD24." (PMID 40486886, 2025). "CD44 and CD24 are cell surface proteins, and their expression patterns are used to identify and characterize cancer stem cells (CSCs)." (PMID 40227834, 2025). "In this review, we summarized the basic characteristics and functions of CD24, as well as its role in the development of cancer." (PMID 40486886, 2025). "CD24 is a cell surface glycoprotein that is overexpressed in different cancer cells and contributes significantly to cancer-related mortality." (PMID 41378821, 2025). "Surviving MCF-7 cancer cells further showed high CD44 and low CD24 gene expression, a cancer stem cell phenotype that has been described to be promoted by polyclonal allogenic T cells." (PMID 40240529, 2025). "The availability of anastasis markers such as cell surface CD24 expression will hopefully lead to addressing this and other outstanding questions in cancer progression and therapy." (PMID 41226542, 2025). "Our results showed that MBZ significantly down-regulated cancer stemness markers, including CD24, CD44, and EpCAM, in both OVCAR3 and OAW42 cells, but the effects were more pronounced in OVCAR3 cells." (PMID 39851541, 2025). "The results showed that CEACAM6 and CD24 were specifically highly expressed in cancer stem cell (CSC)." (PMID 40860182, 2025). "While proteins, such as EpCAM and CD24, were among the first biomarkers studied in EVs derived from malignant ascites, more recent works have explored the EVs biocargo, focusing particularly on miRNAs." (PMID 40259212, 2025). "In view of the high expression of CD24 in cancer cells and the role of inducing resistance in chemoradiotherapy, CD24 is considered a promising new target for cancer treatment." (PMID 40486886, 2025). "Despite these discouraging examples, a clinical trial testing a Notch signaling pathway inhibitor in BCSCs successfully reduced ALDH+ cells, along with other cancer stem cell markers such as CD44/CD24 and mammosphere-forming efficiency." (PMID 40869256, 2025). "CD24, formerly known as glycosylated mucin‐like cell surface protein, is a newly identified antiphagocytic molecule that can be harnessed by cancer cells to avoid attack from Siglec‐10‐expressing macrophages." (PMID 41354057, 2025).
cancer (continued). "Considering the multifaceted characteristics of CD24 in promoting cancer progression, facilitating immune evasion, and inducing resistance to radiochemotherapy, we believe these mechanisms are closely interconnected." (PMID 40486886, 2025). "Subsequently, we discuss the manifestations and mechanisms of radiotherapy and chemotherapy resistance mediated by CD24, summarize the research on cancer immunotherapy targeting CD24, and propose future research directions and solutions for this issue." (PMID 40486886, 2025). "In docetaxel-resistant TNBC cells, KIF11 knockdown inhibited the proliferation of CD44+/CD24-cancer stem-like cells and removed their self-renewal capacity." (PMID 41487287, 2025). "CD24 has been shown to play diverse functional roles in immunity, cancer, inflammation, and autoimmune diseases." (PMID 40783744, 2025). "PPAB001 is a bispecific antibody fusion protein designed to simultaneously target and block CD47 and CD24, two critical immune checkpoints that inhibit macrophage-mediated phagocytosis of cancer cells." (PMID 40330466, 2025). "The cell surface expression of CD24 has been recently reported to be preferentially enriched in anastatic cancer (melanoma) cells that exhibit tumorigenic properties." (PMID 41226542, 2025). "The in vivo analysis of cancer stem cell (CSC) markers revealed a noticeable but borderline significant reduction in CD24 expression in both seaberry-treated groups." (PMID 40371330, 2025). "CD24 functions as a “don't eat me” signal, inhibiting inflammation and preventing phagocytosis of cancer cells by interacting with Siglec‐G/10 on macrophages." (PMID 40836885, 2025). "The CD24+ and neuronal-like clusters, representing cancer stem cells, were enriched for proliferative gene sets, DNA repair mechanisms, and β−catenin signaling." (PMID 41444249, 2025). "Treatment with the MELK inhibitor OTSSP167 significantly reduced mammosphere formation efficiency in cancer stem cell populations (CD44+/CD24− and ALDH+) compared to untreated controls." (PMID 40076867, 2025). "After Nab-PTX + pembrolizumab, MDSCs cocultured with TTN-KO cancer cells attenuated apoptosis and increased CD24 + CD44 + cell subpopulations in TNBC." (PMID 41326912, 2025). "With increased understanding of cancer immunological mechanisms, particularly the role of “don’t eat me” CD24/Siglec10 signaling, we propose that CD24 blockade is a promising strategy for cancer treatment." (PMID 40486886, 2025). "Considering the positive results of CD24 in preclinical and clinical studies, targeting CD24 in combination with chemotherapy is a hopeful strategy for cancer treatment." (PMID 40486886, 2025). "Here, we introduce the basic characteristics and functions of CD24, as well as its role in the progression of cancer." (PMID 40486886, 2025). "Targeting CD24 represents a promising new avenue in cancer immunotherapy, with unique advantages, especially in overcoming immune evasion." (PMID 40486886, 2025). "CD24's interaction with P-selectin has been demonstrated to facilitate cancer cell adhesion to endothelial cells, promoting pulmonary metastasis." (PMID 40783744, 2025). "Despite extensive research on the role of miR-216a-5p in PDAC and other types of cancer, its potential connection with PaCSCs and their associated markers CD44/CD24/CxCR4 and ALDH1 remains unexplored." (PMID 40243417, 2025). "Up to now, two clinical trials utilizing CD24-targeted immunotherapy in cancer patients have been completed." (PMID 40486886, 2025). "The cell surface expression of CD24 has recently been reported to be preferentially enriched in recovered (anastatic) cancer cells that exhibit tumorigenic properties." (PMID 40076508, 2025). "For example, we observed loops linking enhancers to the increased expression of CD24 for V137D, and to decreased expression of RPP25 for cancer variant R118G, relative to both WT and LoF controls." (PMID 38968069, 2024).
cancer (continued). "Further development should consider other immune- and cancer-related functions of CD24 and additional CD24 and Siglec-10 ligands binding to different glycosylated protein forms." (PMID 38831013, 2024). "For example, combinations of different markers, such as CD133, CD44, CD24, and ALDH, have been reported to be associated with cancer stem cell properties; however, highly sensitive and specific markers for CSCs remain elusive." (PMID 38831317, 2024). "Anti-CD24 antibodies that block the interaction with its ligand Siglec-10, expressed on macrophages and other innate immune cells, increase phagocytosis of cancer cells by macrophages, with encouraging results in early-phase clinical trials." (PMID 38690738, 2024). "Targeting CD24 aims to dismantle these protective mechanisms, potentially making cancer cells more vulnerable to treatment by enhancing immun2e response, reducing cancer stem cell renewal, and increasing the effectiveness of chemotherapy and targeted drugs." (PMID 38881902, 2024). "It is worth noting that the available data in this area are quite limited, and further research is necessary to gain a better understanding of the role of autophagy in cancer and the involvement of CD24 in this process." (PMID 38881902, 2024). "ELF5, as a transcription factor, induces CD24 expressions at the transcription level, CD24 high expression promotes the proliferation and invasion of cancer cells." (PMID 38914670, 2024). "One of the most common uses of CD44 in the cancer field is with CD24 as cell-surface markers of breast and other cancer stem cells." (PMID 38539529, 2024). "High CD24 levels have been identified as adverse prognostic factors for progression-free and cancer-specific survival in NSCLC patients." (PMID 38962009, 2024). "Exploiting this viral sensitivity to CD24 offers the possibility of its use as a prognostic target for a broad population of expressing cancers, many of which have shown resistance to current clinical therapies." (PMID 38214542, 2024). "In the T47D cell line, the three control samples exhibited an average expression of 10.5% of CD44 + /CD24-, which are markers commonly found in cancer stem cells (CSCs), within the total cell population." (PMID 38744871, 2024). "Within the clinical practice and oncology research, several clinically established cancer stem cell markers exist, including CD24, CD44, CD133, ALDH1, and EpCAM." (PMID 39435289, 2024). "The ANRS consists of five ANRGs: SPIB, CD24, NTRK3, EDA2R, and PLK1, all of which have been extensively linked to cancer." (PMID 39596658, 2024). "Specifically, the interaction between the transcriptional co-activator YAP and the CD24 surface molecule delineates a novel mechanism through which cancer cells circumvent immunological destruction." (PMID 38881902, 2024). "It addresses the limitations imposed by the CD24/Siglec-10 pathway and offers a new avenue for more effective cancer treatments." (PMID 39479443, 2024). "In recent years, there has been growing interest in CD24 as a potential therapeutic target for cancer treatment." (PMID 38881902, 2024). "CD24 is emerging as a pivotal modulator in the immune evasion mechanisms of cancer cells, acting as a novel phagocytosis checkpoint that manipulates the immune system to recognize and eliminate malignant cells." (PMID 38881902, 2024). "Then we highlight the ongoing clinical advancements in the targeting CD24 and identify the challenges and potential solutions in the context of cancer immunotherapy." (PMID 38881902, 2024). "In non-small cell lung cancer, CD24 expression serves as an independent marker for the overall survival of cancer patients." (PMID 38881902, 2024). "CD24 is a protein found on the surface of cells that plays a crucial role in the proliferation, invasion, and spread of cancer cells." (PMID 38487533, 2024).
cancer (continued). "This review addresses the properties and mechanisms of CD24/Siglec-10-targeted immunotherapy and provides an overview of recent developments in CD24/Siglec-10-related research in cancer immunotherapy." (PMID 38279998, 2024). "This review summarizes the current knowledge of CD24, including its structure, function, and its role in cancer." (PMID 38881902, 2024). "CD47 and CD24 function as innate ICs, diminishing the phagocytic action of macrophages on cancer cells in a synergistic manner." (PMID 38971872, 2024). "Recently, an ever-growing number of studies have observed cytoplasmic accumulation of CD24 in samples from cancer patients." (PMID 39791710, 2024). "Although the use of CD24 as a immune checkpoint receptor target for cancer immunotherapy is still in its early stages, clinical trials have shown promising results." (PMID 38487533, 2024). "Thirdly, expression of CD24 can vary significantly between different types of cancer and between patients." (PMID 38881902, 2024). "CD24 signaling, through Siglec-10 macrophages, is a target for cancer immunotherapy and is related to the mutant-IDH1-dependent chromatin state." (PMID 39619148, 2024). "CD24 is a cell surface protein that is expressed on a variety of cell types, including immune cells, neural cells, and cancer cells." (PMID 38881902, 2024). "Studies indicate that blocking CD24 can boost the effectiveness of cancer treatments like sorafenib." (PMID 38881902, 2024). "Preclinical research has demonstrated the promise of CD24 inhibition as a targeted cancer immunotherapy for several malignancies." (PMID 38279998, 2024). "Through its interaction with the inhibitory receptor Siglec-10 on macrophages, CD24 effectively sends a “don’t eat me” signal, thereby preventing the phagocytosis of cancer cells." (PMID 38881902, 2024). "The results showed that CD24 was expressed in all cancer cell lines, with the highest levels observed in BRCA cell lines." (PMID 39791710, 2024). "The activation of YAP, and its subsequent effect on CD24 expression, further enhances this evasion by effectively modulating the immune system’s ability to recognize and eliminate cancer cells." (PMID 38881902, 2024). "CoQ0 prevents cancer stem-like characteristics (upregulated CD24 expression and downregulated CD44, ALDH1, and OCT4) under normoxia and/or hypoxia." (PMID 38904007, 2024). "CD24, a glycoprotein expressed on cancer cells, interacts with Siglec receptors on immune cells, inhibiting their activation and promoting immune evasion." (PMID 39040441, 2024). "This demonstrates that viral sensitivity is CD24 dependent and advances the option for its use as a prognostic marker in an array of human cancers, offering an alternative therapy for both primary and multidrug-resistant recurrent cases." (PMID 38214542, 2024). "CD24 is a cell surface molecule that is highly expressed on various cancer cells but has low expression on normal cells." (PMID 39013849, 2024). "We have also confirmed CD24 on cancer cells as a sialoglycan ligand that interacts with Siglec‐G on T cells." (PMID 39373395, 2024). "CD24 regulates cell migration, invasion, and cell proliferation, and has been shown to be highly expressed on different types of cancer cells of solid tumors." (PMID 39324141, 2024). "Starting from the day before injection of cancer cells into the spleen, mice were given intravenous injections of IgG control, anti-CD24 mAb, SAMIs, and PAC-SABIs every other day for a total of 4 doses." (PMID 38971872, 2024). "Siglec-10, which interacts with sialylated CD24 in some cancers, triggers a potent immune suppression pathway in TAMs." (PMID 38254780, 2024). "Altogether, bioinformatics analysis revealed that CD24 is upregulated in most cancers and is widely distributed in the membrane, cytoplasm, and nucleus." (PMID 39791710, 2024).